ZHX2 (zinc fingers and homeoboxes 2)
Diseases named in the same sentence as ZHX2 in open-access papers (continued):
Sharing a sentence is not in itself a finding about the gene and the disease.
multiple myeloma (7 papers, 2015 to 2022). "Other studies indicate the association of increased ZHX2 expression with improved response to high dose chemotherapy in multiple myeloma." (PMID 25473899, 2015). "Consistent with findings in HCC, low ZHX2 expression correlates with poor prognosis of thyroid cancer, multiple myeloma, and chronic lymphocytic leukemia." (PMID 36465389, 2022). "To clarify the mechanisms of ZHX2 affecting the sensitivity of myeloma cell to BTZ, we determined NF‐κB expression in cytoplasm and nucleus after ZHX2 knock‐down." (PMID 32780537, 2020). "In this study, we reported that ZHX2 regulates the nuclear translocation of NF‐κB and proteasome inhibitor resistance in myeloma cell, providing a new mechanism of proteasome inhibitor resistance." (PMID 32780537, 2020). "In conclusion, our study showed that ZHX2 can regulate the nuclear translocation of NF‐κB and is related to myeloma cells’ resistance to proteasome inhibitor." (PMID 32780537, 2020). "We found that ZHX2 can regulate the nuclear translocation of NF‐κB and is related to myeloma cell resistance to proteasome inhibitor." (PMID 32780537, 2020). "ZHX2 is a B-cell specific factor that plays a role in differentiation and apoptosis, where through expression analyses, it was found in hematopoietic cell lines and primary cells that ZHX2 acts as a tumour suppressor for HL and multiple myeloma." (PMID 29487724, 2018). "Other studies have also reported that increasing the ZHX2 expression could improve the response to high-dose chemotherapy in multiple myeloma." (PMID 36232466, 2022). "The multiple myeloma patients with lower ZHX2 expression have worse outcomes." (PMID 36232466, 2022). "Furthermore, ZHX2 expression is closely related to the malignancy and poor prognosis of B-cell lymphoma, myeloma, lung cancer, and thyroid cancer, suggesting that ZHX2 plays an important role in tumorigenesis and cancer development." (PMID 36465389, 2022). "As ZHX2 is a regulator of NF‐κB activation and can be degraded by proteasome, we hypothesize that ZHX2 may affect myeloma sensitivity to proteasome inhibitor." (PMID 32780537, 2020). "ZHX2 is a transcription regulator degraded via proteasome and presents both oncogenic or tumor suppressive effect in different cancers, however, it is still unknown that the role of ZHX2 in myeloma." (PMID 32780537, 2020). "Interestingly, high ZHX2 expression is significantly associated with an improved response and longer survival after high dose-chemotherapy in patients with multiple myeloma, suggesting that ZHX2 might influence drug resistance in cancer cells." (PMID 25473899, 2015).
atherosclerosis (6 papers, 2014 to 2023). A disease characterized by the build-up of fatty material and calcium deposition in the arterial wall resulting in partial or complete occlusion of the arterial lumen. "In vascular tissues, one of the top KDs for the shared CAD/atherosclerosis pathways between species is ZHX2, whose subnetwork neighbors are highly enriched for genes in a co-expression module annotated with RXR/VDR pathway, post translational protein modification, and endocytosis terms." (PMID 38060277, 2023). "Interestingly, we detected differential expression of ZHX2, a regulator of plasma lipid metabolism that is the closest gene to the top SNP locus from a recent atherosclerosis GWAS meta-analysis." (PMID 24628908, 2014). "Furthermore, TFs, including nuclear factor kappa beta (NF-κB), PU.1, the Ets-1 family, activator protein 1 (AP1), Krϋppel-like factor 2 (KLF2), zinc fingers and homeoboxes 2 (Zhx2), and activating transcription factor 4 (ATF4), play a critical role in atherosclerosis." (PMID 35645372, 2022).
lung carcinoma (6 papers, 2020 to 2025). "High ZHX2 mRNA level was observed to be associated with a better OS rate in patients with lung cancer." (PMID 41480542, 2025). "This founding demonstrates a tumor-suppressor role of ZHX2, consistent with another report in lung cancer suggesting ZHX2 represses proliferation and increases apoptosis of tumor cells via inactivation of p38MAPK signaling." (PMID 41480542, 2025). "Mechanically, ZHX2 acts as a tumor suppressor in lung cancer by inhibiting the p38MAPK signaling pathway." (PMID 36232466, 2022). "ZHX2 inhibits proliferation and promotes apoptosis of lung cancer cells by inhibiting the p38-MAPK signaling pathway." (PMID 36465389, 2022). "In line with our findings, overexpression of ZHX2 reduced the migratory ability of lung cancer cells via the p38MAPK signalling pathway." (PMID 35151335, 2022). "For example, ZHX2 expression was significantly reduced in the human lung cancer cell lines." (PMID 36232466, 2022). "Furthermore, elevated ZHX2 exhibited an improved PPS rate in patients with lung cancer." (PMID 41480542, 2025). "Similarly, we found that high ZHX2 expression was not only correlated with a prolonged OS, but also indicated a better PPS rate in patient with lung cancer." (PMID 41480542, 2025). "Additionally, analysis from the CCLE database demonstrated that the mRNA levels of ZHX1, ZHX2 and ZHX3 in lung cancer cell listed in the 19th, 25th, and 10th highest positions across all types of cancer, respectively." (PMID 41480542, 2025).
thyroid cancer (6 papers, 2021 to 2025). "One study indicates that ZHX2 inhibits thyroid cancer metastasis by inhibiting calcium-binding protein expression at the transcriptional level." (PMID 39940256, 2025). "Adjacent non-tumour tissues (referred to as P) showed higher levels of ZHX2 protein than thyroid cancer tissues (referred to as T)." (PMID 35151335, 2022). "Here, we observed that ZHX2 protein levels negatively correlated with the protein levels of vimentin and N-cadherin, and positively correlated with the protein levels of E-cadherin, indicating that ZHX2 restrains the migration of thyroid cancer cells." (PMID 35151335, 2022). "Inhibition of S100A14 attenuated the ZHX2 knockdown-induced enhanced metastasis of thyroid cancer cells both in vitro and in vivo." (PMID 35151335, 2022). "The evidence presented here suggests that ZHX2 inhibits the progression of thyroid cancer by blocking S100A14-mediated metastasis." (PMID 35151335, 2022). "Nevertheless, our data demonstrated that ZHX2 inhibits thyroid cancer metastasis by repressing S100A14 expression at the transcriptional level." (PMID 35151335, 2022). "More importantly, knockdown of S100A14 attenuated ZHX2 silencing-induced thyroid cancer cell migration both in vitro and in vivo." (PMID 35151335, 2022). "Based on bioinformatics analysis, we found that ZHX2 negatively correlated with S100A14 in thyroid cancer." (PMID 35151335, 2022). "Here, we found that knockdown of S100A14 abolished ZHX2 silencing-induced cell migration both in vitro and in vivo, demonstrating that ZHX2 is involved in thyroid cancer metastasis through S100A14." (PMID 35151335, 2022). "We investigated the role of the tumour suppressor zinc fingers and homeoboxes 2 (ZHX2) in the metastasis of thyroid cancer." (PMID 35151335, 2022). "ZHX2 expression was significantly decreased in thyroid cancer tissues, which correlated with poor prognosis of thyroid cancer patients." (PMID 35151335, 2022). "To further investigate the role of ZHX2 in thyroid cancer metastasis, we measured the migration ability of thyroid tumour cell lines with modulated levels of ZHX2." (PMID 35151335, 2022). "To study the role of ZHX2 in thyroid cancer metastasis, we evaluated the EMT process using both in vitro and in vivo models." (PMID 35151335, 2022). "The inhibition of S100A14 attenuated thyroid cancer cell metastasis induced by ZHX2 knockdown in cultured cells and in animal models." (PMID 36232466, 2022). "Further wound healing assays also showed that cell motility was reduced in ZHX2-overexpressing thyroid cancer cell lines and increased in ZHX2 knockdown thyroid cancer cell lines." (PMID 35151335, 2022). "To further evaluate the location and expression of ZHX2 protein on thyroid cancer cells, we detected ZHX2 protein in thyroid cancer tissues using immunohistochemistry (IHC)." (PMID 35151335, 2022). "To further confirm that ZHX2 restrains thyroid cancer metastasis via S100A14, we performed lung metastasis assays in mouse models." (PMID 35151335, 2022). "Further study showed that silencing ZHX2 increased cell migration and wound healing in thyroid cancer cell lines." (PMID 35151335, 2022). "We found that overexpression of ZHX2 significantly restrained the thyroid cancer metastatic process, inhibiting wound healing and the migration of thyroid cancer cells." (PMID 35151335, 2022). "To study the role of ZHX2 in thyroid cancer metastasis, we evaluated the EMT process using cell migration, wound healing and lung metastatic tumour formation in vitro and in vivo models." (PMID 35151335, 2022). "Zn fingers (ZHX2), or transcription factors, play an important role in thyroid cancer development." (PMID 39940256, 2025). "ZHX2 overexpression vector or siRNAs were transfected into thyroid cancer cell lines." (PMID 35151335, 2022). "It was also reported that ZHX2 inhibited the progression of thyroid cancer." (PMID 36232466, 2022). "ZHX2 knockdown significantly promoted the migration of thyroid cancer cells." (PMID 35151335, 2022).
thyroid cancer (continued). "Above all, ZHX2 inhibits thyroid cancer migration via S100A14." (PMID 35151335, 2022). "The knockdown of ZHX2 significantly promoted thyroid cancer cell migration." (PMID 36232466, 2022). "Together, these results show that ZHX2 expression is decreased in thyroid cancer." (PMID 35151335, 2022). "It is possible that ZHX2 regulates thyroid cancer metastasis through multiple pathways." (PMID 35151335, 2022). "Recently, whole transcript microarray expression profiling detected the common expression of ZHX2 in brain metastatic PTC and primary brain tumours, suggesting that ZHX2 may play a role in thyroid cancer metastasis." (PMID 35151335, 2022). "To verify whether the inhibition of thyroid cancer migration by ZHX2 was achieved by repressing S100A14, we performed the following experiments." (PMID 35151335, 2022). "Furthermore, ZHX2 inhibits thyroid cancer metastasis and is responsible for reduced chemotherapy resistance in HCC." (PMID 36465389, 2022). "One of the important questions is how ZHX2 inhibits the metastasis of thyroid cancer." (PMID 35151335, 2022). "The decreased ZHX2 expression in thyroid cancer tissues was correlated with poor outcomes." (PMID 36232466, 2022). "Moreover, S100A14 was highly expressed in human thyroid cancer samples, and its expression negatively correlated with ZHX2 expression." (PMID 35151335, 2022). "Above all, the data demonstrate that ZHX2 restrains the migration of thyroid cancer cells." (PMID 35151335, 2022). "Since ZHX2 is a well-known transcription factor, we examined S100A14 mRNA levels in thyroid cancer cell lines with ZHX2 manipulation." (PMID 35151335, 2022). "In conclusion, we identified S100A14 as a new target of ZHX2 and revealed that ZHX2 bound to the S100A14 promoter to repress its transcription, which in turn inhibited thyroid cancer metastasis." (PMID 35151335, 2022). "However, whether and how ZHX2 is involved in the progression of thyroid cancer is unknown." (PMID 35151335, 2022). "Therefore, strategies aiming to manipulate ZHX2 and S100A14 might be helpful to treat thyroid cancer." (PMID 35151335, 2022). "However, the role of ZHX2 in thyroid cancer has not been reported." (PMID 35151335, 2022).
triple-negative breast carcinoma (6 papers, 2021 to 2025). An invasive breast carcinoma which is negative for expression of estrogen receptor (ER), progesterone receptor (PR), and human epidermal growth factor receptor 2 (HER2). "This study suggested that in triple-negative breast cancer, ZHX2 deletion promotes a hybrid MET state and attenuates metastasis by regulating E-cadherin transcription." (PMID 37460540, 2023). "Results presented in this paper highlighted ZHX2 function in maintaining the hybrid E/M phenotype by regulating the transcription of epithelial marker, E-cadherin, in triple-negative breast cancer." (PMID 37460540, 2023). "ZHX2 is important for triple-negative breast cancer (TNBC) cell proliferation and tumorigenesis in vivo." (PMID 34779768, 2021). "Zinc Fingers and Homeoboxes 2 (ZHX2) are highly expressed in triple-negative breast cancer (TNBC)." (PMID 38396737, 2024). "ZHX2 is essential for triple-negative breast cancer (TNBC) cell proliferation and invasion." (PMID 34779768, 2021). "Identification of important sites on ZHX2 that may affect its function in triple-negative breast cancer (TNBC)." (PMID 34779768, 2021). "ZHX2 regulates hypoxia-inducible factor (HIF) signaling in triple-negative breast cancer (TNBC)." (PMID 34779768, 2021). "ZHX2 is amplified in triple-negative breast cancer (TNBC) and is potentially regulated by pVHL." (PMID 34779768, 2021). "In addition, it has been found that ZHX2 may promote HIF1α oncogenic signaling in triple-negative breast cancer (TNBC) and hypoxia-induced phase separation of ZHX2 may alter chromatin looping to promote metastasis." (PMID 41480542, 2025). "ZHX2 and HIF cooperate to drive cancer cell proliferation in triple-negative breast cancer." (PMID 39850947, 2024).
gastric cancer (5 papers, 2017 to 2025). A primary or metastatic malignant neoplasm involving the stomach. "For example, the reduced ZHX1 expression was associated with TNM stage progression in gastric cancer, and a reduction in nuclear ZHX2 expression was associated with short survival in HCC." (PMID 28152006, 2017). "A similar phenomenon is found in studies of multiple osteosarcoma and gastric cancer, where high expression of ZHX2 shows a significant correlation with poor survival." (PMID 36465389, 2022). "By contrast, gastric cancer patients with a decreased ZHX2 and ZHX3 mRNA expression showed better outcomes." (PMID 36232466, 2022). "An in vitro experimental study showed that ZHX2 overexpression can facilitate gastric cancer cell proliferation and migration and can suppress cell apoptosis." (PMID 36232466, 2022). "For example, LAMA4, SFRP family members, ZHX2, and PAFAH1B3 were found to be associated with immune infiltration of gastric cancer." (PMID 35252219, 2021). "ZHX1 has been reported to induce apoptosis and cell cycle arrest (G1/S) by regulating cyclin D1, cyclin E, Bcl2, Bax, and cleaved caspase-3 in gastric cancer, and ZHX2 overexpression was correlated with low expressions of cyclin A and cyclin E in HCC." (PMID 28152006, 2017). "In addition, the reduced expression of ZHX2 was associated with a favorable overall survival rate in gastric cancer patients who only received surgery, but not in the patients who received additional therapies." (PMID 36232466, 2022). "In gastric cancer (GC), ZHX2 also exerts an oncogenic function." (PMID 36232466, 2022). "Taken together, these data suggest that ZHX2 and ZHX3 act as oncogenes in gastric cancer." (PMID 36232466, 2022). "On the contrary, ZHX2 promotes the development of ccRCC, TNBC, and gastric cancer." (PMID 36465389, 2022). "Reduced ZHX2 and ZHX3 expression was remarkably correlated with a longer survival time in the subgroups of GC patients without lymph node metastases or distant metastasis, suggesting that the low expression of ZHX2 and ZHX3 predicts a better prognosis for early-stage gastric cancer patients." (PMID 36232466, 2022). "Subgroup analyses also found that the downregulation of ZHX2 was predictive of an improved survival time in HER2-positive gastric cancer patients, but not in HER2-negative gastric cancer patients." (PMID 36232466, 2022).
Hodgkins lymphoma (5 papers, 2015 to 2022). A heterogeneous group of malignant lymphoid neoplasms of B-cell origin characterized histologically by the presence of Hodgkin and Reed-Sternberg (HRS) cells in the vast majority of cases. "ZHX2 has also been reported as a tumor suppressor in Hodgkin lymphoma, where the recurrent breakpoint at 8q24 targets ZHX2." (PMID 36232466, 2022). "STAT1 (signal transducer and activation of transcription 1) and several STAT1 target genes were included, suggesting that ZHX2 functions as a tumor suppressor in Hodgkin lymphoma." (PMID 36232466, 2022). "Spectral karyotyping identified chromosomal rearrangement far upstream region of ZHX2 gene in Hodgkin lymphoma and this aberration results in ZHX2 silencing." (PMID 36465389, 2022). "In Hodgkin’s lymphoma, ZHX2 expression was diminished and ZHX2 knockdown suppressed genes promoting differentiation and apoptosis." (PMID 27835650, 2016). "In Hodgkin lymphoma (HL) we recently reported that deregulated homeobox gene MSX1 mediates repression of the B-cell specific transcription factor ZHX2." (PMID 26406991, 2015). "Multiple mechanisms might be involved in the suppression of ZHX2 expression in Hodgkin lymphoma cell lines." (PMID 36232466, 2022).
Sepsis (4 papers, 2021 to 2024). Sepsis is defined as life-threatening organ dysfunction caused by a dysregulated host response to infection. "In mice with myeloid-specific Zhx2 knockout, there is greater resistance to cecal ligation and puncture as well as LPS-induced sepsis, manifested by prolonged survival, reduced lung injury, and decreased levels of pro-inflammatory cytokines and lactate." (PMID 39712019, 2024). "Several studies have demonstrated that the transcription factors hypoxia-inducible factor 1α and zinc fingers and homeoboxes 2 can transcriptionally upregulate Pfkfb3 in the context of sepsis." (PMID 38705396, 2024). "Also, PFKFB3 has been shown to be a target of the zinc fingers and homeoboxes 2 (ZHX2) transcription factor and, as a result, to accelerate disease progression in models of sepsis." (PMID 34044589, 2021). "Transcription factor Zhx2 enhances PFKFB3 transcription by binding to the PFKFB3 promoter, thereby contributing to macrophage metabolic reprogramming and accelerating sepsis progression." (PMID 39712019, 2024).
chronic lymphocytic leukemia (3 papers, 2021 to 2022). "The prognostic impact of ZHX1 and ZHX2 in chronic lymphocytic leukemia (CLL) has recently been reported." (PMID 36232466, 2022).